UCP1 (uncoupling protein 1)
Diseases named in the same sentence as UCP1 in open-access papers (continued):
Sharing a sentence is not in itself a finding about the gene and the disease.
breast carcinoma (continued). "We conclude that UCP1 is up-regulated in breast cancer cell lines and primary breast as well as other tumors." (PMID 21935467, 2011). "We next tested whether UCP1-CRISPRa primary breast adipocytes can suppress breast cancer growth in vivo." (PMID 39905264, 2025). "Moreover, UCP1 was reported to regulate the stemness of breast cancer stem cells through glycometabolism key enzyme FBP1 and ALDH 12, revealing various functions of UCP1 in the breast cancer process." (PMID 35541900, 2022). "It suggested a potential effect of UCP1 on the repression of breast cancer." (PMID 35541900, 2022). "Expression of UCP1 was also found in neuroendocrine carcinoma (red arrow, 100X and 400X), and rare expression in invasive lobular carcinoma, another malignant subtype of breast cancer." (PMID 35541900, 2022). "In order to investigate the potential downstream target of UCP1 on the process of breast cancer, we detected whether the overexpressed UCP1 protein is located in mitochondria to exert its function in breast cancer." (PMID 35541900, 2022). "Two types of triple-negative breast cancer cell lines, MDA-MB-231 and BT549, were chosen as target cell lines to investigate whether the overexpression of UCP1 could inhibit the malignant behavior of breast cancer." (PMID 35541900, 2022). "Subcutaneously injecting mammary tumor fraction depleted for UCP1+ adipocytes into nude mice significantly reduced tumor growth, suggesting that beige adipocytes may contribute to breast cancer development." (PMID 35186923, 2022). "Invalidation of ADM in breast cancer cells dramatically reduced UCP1 expression in adipocytes." (PMID 32819314, 2020). "We demonstrated that breast cancer cells can undergo thermogenesis through UCP1 induction." (PMID 32647572, 2020). "The mutually exclusive relationship between FABP7 and UCP1 expression suggested that FABP7 could negatively regulate UCP1-mediated thermogenesis in breast cancer." (PMID 32647572, 2020). "We observed that FABP7 knockdown induced UCP1-mediated thermogenesis in a breast cancer cell line." (PMID 32647572, 2020). "Immunohistochemical staining detected a significant expression of UCP1, in the adenosis sample (normal breast control), on the mammary gland tube (red arrow, 100X and 400X), and a rare expression in invasive ductal carcinoma, a malignant subtype breast cancer with poor prognosis." (PMID 35541900, 2022). "Therefore, we tested whether FABP7 knockdown could affect the differentiation status of breast cancer cells and UCP1-mediated thermogenesis." (PMID 32647572, 2020). "Thus, FABP7-knockdown-induced UCP1 activated autonomous heat production in breast cancer cells." (PMID 32647572, 2020). "Here, we described a new metabolic feature in breast cancer, namely, that blocking hypoxia-inducible FABP7 triggers UCP1-mediated thermogenesis." (PMID 32647572, 2020). "We found a strong mutual exclusivity between FABP7 and UCP1 expression in the METABRIC and TCGA breast cancer cohorts." (PMID 32647572, 2020). "Overall, our results demonstrate that human adipocytes from dissected breast tissue can upregulate UCP1 via AAV9-CRISPRa and are able to reduce glycolysis and fatty acid metabolism and suppress breast cancer organoid growth, both in cell culture and xenografts." (PMID 39905264, 2025). "To examine whether our treatment might provide systematic therapeutic effect in suppressing breast cancer growth, we next used MMTV-PyMT female mice, implanting Ucp1-CRISPRa or dCas9–VP64 adipose organoids near the third nipples of 4-week-old mice." (PMID 39905264, 2025). "For example, in the context of breast cancer research, ADM has been shown to stimulate adipocytes, leading to the upregulation of uncoupling protein 1 (UCP1) expression and the enhanced phosphorylation of hormone-sensitive lipase (HSL), which in turn activates lipolysis." (PMID 40565016, 2025).
breast carcinoma (continued). "Data collected from TCGA showed expression of UCP1 decreased significantly on major breast cancer subclasses, like HER2+ and triple-negative, rather than on normal breast tissue." (PMID 35541900, 2022). "The mitochondrial protein showed therapeutic potential on breast cancer, whereas the mechanism and downstream pathway of mitochondrial uncoupling protein 1 (UCP1) was not fully elucidated." (PMID 35541900, 2022). "Although several studies have reported ectopic UCP1 expression in multiple cancers, including breast cancer, the functionality of UCP1 has never been elucidated." (PMID 32647572, 2020). "There is also a striking correlation of expression of each gene with specific types of breast cancer, ER positive to UCP1, and ER negative to FABP7." (PMID 32647572, 2020). "In contrast to these in vitro experimental results, we found no substantial correlation of FABP7 and UCP1 expression on patient survival in the METABRIC and TCGA breast cancer cohorts." (PMID 32647572, 2020).
hyperlipidemia (11 papers, 2012 to 2024). "Thus, the sympathetic activation-UCP1 axis is involved in cold-associated hyperlipidemia that contributes to cold-induced accelerated development of atherosclerotic plaques." (PMID 23823482, 2013). "FGF19 not only reduced HFD‐induced body weight gain, excessive lipid accumulation and hyperlipidaemia but also promoted energy expenditure (PGC‐1α, UCP‐1, PPAR‐γ) in brown adipose tissue (BAT)." (PMID 33751819, 2021).
Sepsis (8 papers, 2013 to 2026). Sepsis is defined as life-threatening organ dysfunction caused by a dysregulated host response to infection. "At 22 °C, Tb was maintained during mild sepsis but dropped during severe sepsis, linked to reduced UCP1 expression in brown adipose tissue and less effective vasoconstriction." (PMID 39522078, 2024). "In contrast, obese mice exhibit resistance to sepsis- and NE-induced browning due to reduced β-3ARs expression in adipose tissue: UCP1 levels remain low, inflammatory factor levels and blood pH are more stable, and organ damage is significantly alleviated." (PMID 41498391, 2026). "During mild sepsis, we observed a more consistent tail vasoconstriction and an increase in UCP1 expression in the BAT." (PMID 39522078, 2024). "Despite the high fever, our results showed that at 12 h after the CLP surgery, there is a decrease in BAT UCP1 during severe sepsis." (PMID 39522078, 2024). "Interestingly, UCP1, PPAR-α, and PGC-1α are closely associated with sepsis-related mitochondrial damage." (PMID 39549609, 2024). "However, UCP1 levels were similar in the sham and mild sepsis groups." (PMID 39522078, 2024). "Sepsis induced significant WAT browning in non-obese mice, as evidenced by marked upregulation of UCP1 expression, while obese mice showed strong resistance to sepsis-induced WAT browning with notably lower UCP1 expression than non-obese septic mice." (PMID 41498391, 2026). "As BAT UCP1 expression was not altered in mild sepsis and had a decrease after severe sepsis, we infer that fever was mediated by tail vasoconstriction rather than an increase in non-shivering thermogenesis." (PMID 39522078, 2024). "Specifically, HLI was reduced in all septic animals, regardless of Ta, while UCP-1 expression in brown adipose tissue increased only in mild sepsis under subthermoneutral conditions." (PMID 39522078, 2024). "On the other hand, in severe sepsis, UCP1 levels did not change and HLI was reduced only 10 h after CLP, which potentially contributed to the reduction in body temperature." (PMID 39522078, 2024). "In addition, UCP1 expression in BAT was significantly increased 12 h after mild sepsis, but not in the 10-punctures CLP group." (PMID 39522078, 2024).
breast tumors (7 papers, 2011 to 2025). "As such, UCP1 expression in breast tumors likely reflects not only intrinsic cancer cell metabolism, but also the individual’s systemic metabolic state, the extent of BAT activity, and the degree of WAT browning within the breast tissue microenvironment." (PMID 40983641, 2025). "Furthermore, UCP1 is more highly expressed in normal mammary epithelium and well-differentiated breast tumors than in poorly differentiated, high-grade tumors, and elevated UCP1 expression is associated with a favorable prognosis." (PMID 40983641, 2025). "In our research, expression of marker genes of fat browning, like UCP1, PRDM16, CIDEA, COX7A1, PGC1α, TMEM26 and TBX1, was up-regulated in adipose tissue adjacent to breast tumors." (PMID 25291184, 2014).
heart failure (7 papers, 2011 to 2026). Inability of the heart to pump blood at an adequate rate to meet tissue metabolic requirements. "As documented by published studies, all of these RKIP-induced Pparg target genes promote symptoms of heart failure and/or cardiac lipid overload, i.e., Adipoq, Cidec, Retn and Ucp1." (PMID 35203304, 2022). "Since increased Adipoq and Ucp1 levels contribute to heart failure pathogenesis, the Grk2 inhibition-induced normalisation of pathologically elevated Adipoq and Ucp1 levels is a desired, positive therapeutic effect and not an adverse effect." (PMID 35203304, 2022). "We found that UCP-1 in BAT reduced with heart failure, and level of beige markers remained low in subcutaneous white adipose tissue." (PMID 36050466, 2022). "Immunoblot detection was used to quantify protein levels of FASN, SCD1 and UCP1 in cardiac tissue specimens from patients with heart failure." (PMID 21711241, 2011). "In agreement with that conclusion, heart biopsy specimens of patients with heart failure showed massive lipid accumulation and high protein levels of key fat metabolizing enzymes FASN, SCD1 and UCP1." (PMID 21711241, 2011). "Heart muscle specimens from patients with heart failure also showed significant levels of UCP1 protein relative to control specimens from patients without heart failure." (PMID 21711241, 2011).
Hyperinsulinemia (6 papers, 2009 to 2021). An increased concentration of insulin in the blood. "Bearing in mind that the protein expression profile in whole tissue does not represent mitochondria-only proteins, we first decided to examine the effects of hyperinsulinemia on key mitochondrial ETC complexes, ATP synthase, and UCP1 protein expression on isolated mitochondria." (PMID 33287103, 2020).
hypothyroidism (6 papers, 2010 to 2022). Abnormally low levels of thyroid hormone. "In addition, these results implicate UCP1 as one of the factors underlying impairment of BAT mitochondrial thermogenesis in hypothyroidism." (PMID 25658324, 2015). "In this study, a decreased gene expression of UCP1, rectal temperature, and the Na+/K+-ATP enzyme were also observed in the hypothyroidism model." (PMID 36091783, 2022). "In addition, Western blotting (8 B) indicated that hypothyroidism significantly decreased mitochondrial UCP1 levels, while T2 administration significantly increased it." (PMID 25658324, 2015). "Decreased levels of UCP-1, the Na+/K+-ATP enzyme, and ACC 1 were observed, which suggested the presence of an energy metabolism imbalance and a disordered lipid metabolism in hypothyroidism rats." (PMID 36091783, 2022). "Additionally, the levels of UCP-1, Na+/K + -ATP enzyme, and ACC1 were ameliorated by the four typical “hot” property herbs in hypothyroidism rats." (PMID 36091783, 2022). "Interestingly, male Trspf/f-Ucp1-Cre+/− mice at room temperature had modest elevation of circulating thyroid-stimulating hormone (TSH), a sign of mild hypothyroidism, in comparison to their Trspf/f counterparts." (PMID 33435397, 2021). "Although TH was considered to be associated with thermogenesis through UCP1 gene expression and D2 in BAT, elevated TSH status before RIT, hyperthyroidism, or hypothyroidism did not significantly impact BAT visualization and the interpretation of clinical FDG-PET/CT images." (PMID 29666563, 2018). "In BAT, we found reduced Klf9 (−34.82%) expression and 2.51-fold increased mRNA levels of Ucp1, the master regulator of brown adipocyte thermogenesis, although Prdm16, the transcriptional coregulator of brown adipocyte differentiation, and Ppargc1a were not regulated by hypothyroidism." (PMID 36143246, 2022).
lung carcinoma (6 papers, 2014 to 2025). "Increased USP18 expression enhanced UCP1 protein expression in lung cancer cell lines by reducing ubiquitination, and the increase in UCP1 expression enhanced cell proliferation." (PMID 39944823, 2025). "Adipocyte browning is suggested to contribute to adipose tissue wasting in different cancer cachexia models such as lung cancer, liver cancer, and PC, all of which demonstrated the intense staining of the thermogenic marker uncoupling protein 1 (UCP1) in subcutaneous WAT (scWAT, mouse SAT)." (PMID 36230682, 2022). "PPARγ can activate AMPK in adipose tissue.AMPK enhances PPARγ deacetylation, thermogenic proteins (UCP-1).Rosiglitazone increases AMPK and AKT in lung cancer models (Muscle Preservation)." (PMID 41476922, 2025).
pheochromocytoma (6 papers, 2011 to 2020). "We assessed that WAT of PWO in basal conditions expressed very low levels of UCP1 mRNA (104/105 times lower) when compared to human VAT surrounding pheochromocytoma that we used as a positive control." (PMID 31440209, 2019). "In fact, pheochromocytoma is an adrenal neoplasm secreting high levels of catecholamines which strongly stimulate browning and UCP1 expression in the adipose tissue." (PMID 31440209, 2019). "BAT is also activated in patients with phaeochromocytoma, (excess catecholamine producing benign adrenal medullary tumour) with increased UCP1 expression similar to levels in cold-exposed rodents." (PMID 26937283, 2014). "In patients with pheochromocytoma, the induction of UCP-1 expression was observed in intra-abdominal adipose tissue." (PMID 21701596, 2011). "It has been shown that retroperitoneal periadrenal fat mitochondria from pheochromocytoma patients have higher OXPHOS than controls and express more UCP1, a marker of BAT." (PMID 32432379, 2020). "We prepared homogenates from biobanked samples used in the reported study and reproduced the results using RIFS, where pheochromocytoma homogenates showed increased ETC activity, mitochondrial mass, UCP1, and ETC protein levels, as described when browning occurs." (PMID 32432379, 2020). "The browning fat of pheochromocytoma patients were confirmed by the enhanced 18F-2-deoxy-2-fluoro-d-glucose uptake by PET/CT scan, tissue morphology, increased mitochondria under electron microscopy, and positive UCP1 protein staining." (PMID 28988979, 2017).
steatosis (6 papers, 2020 to 2025). Increased lipid within the cytoplasm of cells. "The secretion of FGF2 is increased in HFD-induced obese mice while its global knockout mice are resistant to HFD-induced adiposity and steatosis by increasing UCP1-activated thermogenesis, which requires the involvement of heparin." (PMID 40180176, 2025). "Twenty-three of them revealed promising bioactivity on metabolic disorders, especially on lipid reduction on zebrafish embryos, a reduction of steatosis on a cell model, and an increase of ucp1 mRNA expression." (PMID 37755111, 2023). "In this work, we applied a combination of cellular assays (steatosis model, adipocyte differentiation, 2-NBDG uptake), targeted screening (ucp1 mRNA expression), and in vivo screening in zebrafish larvae (Nile red fat metabolism assay)." (PMID 37755111, 2023). "In females, we report negligible impact of UCP1 KO in HF diet-induced steatosis and no significant impact with EPA supplementation in the KO group." (PMID 34829779, 2021). "Our results, showing increased UCP1 protein expression in BAT without improved steatosis, suggest that MBG effects in our model may not be potent enough to reduce liver lipid contents without a significant reduction in caloric intake." (PMID 40297137, 2025).
acute kidney injury (5 papers, 2021 to 2025). Sudden and sustained deterioration of the kidney function characterized by decreased glomerular filtration rate, increased serum creatinine or oliguria. "For instance, the uncoupling protein 1 (UCP1) has been identified as a mediator of lipid depletion in renal cells during acute kidney injury." (PMID 38864666, 2024). "UCP1 ablation has been shown to increase oxidative stress in the kidneys, exacerbating ischemia- or cisplatin-induced acute kidney injury (AKI) in mice." (PMID 40120980, 2025). "Ucp1 is predominantly expressed in brown adipose tissue; however, microarray assays in the mouse kidney have shown that it was also expressed in the renal tubular epithelial cells of normal kidneys, an expression that was dramatically reduced after acute kidney injury." (PMID 39680603, 2024). "Recent studies have demonstrated that the activation of uncoupling protein 1 (UCP1) can mitigate lipid accumulation, thereby attenuating the progression of acute kidney injury via the AMPK/ULK1/autophagy pathway." (PMID 39544947, 2024).
ischemia (5 papers, 2014 to 2026). A hypoperfusion of the BLOOD through an organ or tissue caused by a PATHOLOGIC CONSTRICTION or obstruction of its BLOOD VESSELS, or an absence of BLOOD CIRCULATION. "Moreover, it is reported that during ischemia the level of inhibiting nucleotides (∑ATP + adenosine diphosohate (ADP)) was decreased meanwhile the level of UCP1 activators was increased." (PMID 34709566, 2022). "However, ectopic overexpression of UCP1 in mouse heart was also shown to improve the severity of ischemia-reperfusion injury." (PMID 26770648, 2016).
renal cell carcinoma (5 papers, 2015 to 2025). "Recently, lncRNA COL18A1‐AS1 has been shown to act as a sponge of miR‐1286 to modulate the expression of transcriptional factor Krüppel‐like factor 12 (KLF12), which regulates uncoupling protein 1 (UCP1)‐mediated lipid browning in cell renal cell carcinoma." (PMID 37939296, 2024). "In renal cell carcinoma, melatonin induces a process referred to as “tumor slimming” through the enhancement of lipofuscinosis and autophagy, which is mediated by the peroxisome proliferator-activated receptor gamma coactivator 1 alpha (PGC1α) and uncoupling protein 1 (UCP1) signaling pathway." (PMID 41228459, 2025). "In addition, the PRAT browning process has been specifically detected in renal cell carcinoma (RCC), being characterized by upregulated expression of brown/beige adipocytes markers (UCP1, PPAR-ɣ, c/EBPα, and PGC1α) and downregulated white fat cells markers, such as LEPTIN, SHOX2, HOXC8, and HOXC9." (PMID 40227577, 2025).
central obesity (4 papers, 2012 to 2025). "The A-3826G, A-1766G and Ala64Thr, polymorphisms of UCP-1 gene, were previously associated with weight loss, abdominal obesity and metabolic disorder, which are risk factors of stroke." (PMID 23043591, 2012). "Similarly, patients with central obesity have decreased UCP1 expression, suggesting an association between BAT activity and WAT distribution." (PMID 40868241, 2025). "Male F344 rats also had lower expression of Ucp1 in BAT than other males, a novel finding that is consistent with high adiposity and central obesity." (PMID 37882530, 2023).
colon cancer (4 papers, 2011 to 2022). "It has been verified that expression of uncoupling protein 1 (UCP1), the main functional factor of brown adipose, regulates the growth of aggressive human tumors such as skin carcinoma and colon cancer." (PMID 25291184, 2014). "Chromanes inhibit basal proton conductance of UCP1 and UCP2 and sensitise HT-29 colon cancer cells to commonly used chemotherapeutic agents such as cisplatin and doxorubicin." (PMID 21712825, 2011).
coronary artery disease (4 papers, 2016 to 2025). "It contributes to coronary artery disease (CAD) through local inflammation, while its metabolic activity, including the expression of uncoupling protein-1 (UCP-1) and incretin receptors (GLP-1R, GIPR), may exert protective effects." (PMID 41294813, 2025).